NCOR1 (nuclear receptor corepressor 1)
Description:
Mediates transcriptional repression by certain nuclear receptors. Part of a complex which promotes histone deacetylation and the formation of repressive chromatin structures which may impede the access of basal transcription factors. Participates in the transcriptional repressor activity produced by BCL6. Recruited by ZBTB7A to the androgen response elements/ARE on target genes, negatively regulates androgen receptor signaling and androgen-induced cell proliferation. Mediates the NR1D1-dependent repression and circadian regulation of TSHB expression (By similarity). The NCOR1-HDAC3 complex regulates the circadian expression of the core clock gene ARTNL/BMAL1 and the genes involved in lipid metabolism in the liver (By similarity).
Synonyms: N-CoR; N-CoR1; KIAA1047; hCIT529I10; TRAC1; hN-CoR; MGC104216; PPP1R109
Tractability: Small molecule: a structure with a bound ligand is known; a high-quality ligand is known. PROTAC: UniProt records ubiquitination sites on it; ubiquitination databases record sites on it; its protein half-life has been measured.
Target class: SRC family; Epigenetic regulator; Histone acetyltransferase; Writer
Chemical probes: FK228 (high quality), trichostatin A
Safety:
Unwanted effects reported when the protein is acted on. In parentheses: how it was acted on, where the effect was seen, and who reports it.
Decreased, Body Weight (source: AOP-Wiki)
Gene: Protein-coding gene on chromosome 17 (16,029,065 to 16,218,185, reverse strand). Ensembl gene ENSG00000141027.
Subcellular location: Nucleus
Subcellular location (Human Protein Atlas): Nucleoplasm; Cytosol
Pathways (Reactome):
Signal Transduction: Downregulation of SMAD2/3:SMAD4 transcriptional activity; NOTCH1 Intracellular Domain Regulates Transcription; NR1H2 & NR1H3 regulate gene expression to control bile acid homeostasis; NR1H3 & NR1H2 regulate gene expression linked to cholesterol transport and efflux; Nuclear signaling by ERBB4
Disease: Constitutive Signaling by NOTCH1 HD+PEST Domain Mutants; Constitutive Signaling by NOTCH1 PEST Domain Mutants; HCMV Early Events
Gene expression (Transcription): MLL4 and MLL3 complexes regulate expression of PPARG target genes in adipogenesis and hepatic steatosis; Notch-HLH transcription pathway; Nuclear Receptor transcription pathway
Developmental Biology: Activation of anterior HOX genes in hindbrain development during early embryogenesis; Differentiation of naive CD4+ T cells to T helper 2 cells (Th2 cells); Transcriptional regulation of white adipocyte differentiation
Cellular responses to stimuli: Cytoprotection by HMOX1; Heme signaling
Circadian clock: Expression of BMAL (ARNTL), CLOCK, and NPAS2; RORA,B,C and NR1D1 (REV-ERBA) regulate gene expression
Metabolism: PPARA activates gene expression; Regulation of lipid metabolism by PPARalpha
Chromatin organization: HDACs deacetylate histones
Organelle biogenesis and maintenance: Transcriptional activation of mitochondrial biogenesis
Gene Ontology:
Molecular function: histone deacetylase binding; nuclear receptor binding; protein binding; RNA polymerase II-specific DNA-binding transcription factor binding; transcription corepressor activity; nuclear thyroid hormone receptor binding; transcription cis-regulatory region binding
Biological process: negative regulation of androgen receptor signaling pathway; negative regulation of DNA-templated transcription; negative regulation of fatty acid metabolic process; negative regulation of glycolytic process; negative regulation of JNK cascade; negative regulation of miRNA transcription; negative regulation of transcription by RNA polymerase II; spindle assembly; locomotor rhythm; negative regulation of transcription initiation by RNA polymerase II; regulation of ketone metabolic process
Cellular component: chromatin; histone deacetylase complex; membrane; mitotic spindle; nucleus; transcription repressor complex; nucleoplasm
Genetic constraint (gnomAD): Loss-of-function variants: 58 observed, 246.84 expected, observed/expected ratio (o/e) 0.23, 90% interval 0.19 to 0.29. The upper end of that interval is the gene's LOEUF score, 0.29, which puts it in group 1 of 6, group 1 being the genes least tolerant of losing a copy. Missense variants: 2,248 observed, 2,904 expected, observed/expected ratio (o/e) 0.77, 90% interval 0.75 to 0.8. Synonymous variants: 943 observed, 1,035.6 expected, observed/expected ratio (o/e) 0.91, 90% interval 0.86 to 0.96.
Cancer hallmarks: proliferative signalling (promotes); suppression of growth (promotes); escaping programmed cell death (suppresses); tumour promoting inflammation (suppresses); escaping immune response to cancer; genome instability and mutations; change of cellular energetics; escaping programmed cell death (promotes); invasion and metastasis (suppresses)
Homologues: Orthologues: chimpanzee NCOR1 (99% identical), macaque NCOR1 (99% identical), dog NCOR1 (95% identical), rabbit NCOR1 (93% identical), rat Ncor1 (92% identical), mouse Ncor1 (92% identical), guinea pig NCOR1 (92% identical), pig NCOR1 (87% identical), tropical clawed frog ncor1 (74% identical), zebrafish ncor1 (59% identical), Caenorhabditis elegans gei-8 (13% identical). Paralogues in human: NCOR2 (42% identical).
Diseases named in the same sentence as NCOR1 in open-access papers:
NCOR1 is named in the same sentence as 124 diseases in open-access papers, as found by Europe PMC text mining. Sharing a sentence is not in itself a finding about the gene and the disease. The quoted sentences say what the papers report.
breast carcinoma (51 papers, 2007 to 2025). "The overexpression of coactivators such as SRC1 and the repression of corepressors such as NCoR1 in breast cancer cells have then been associated with tamoxifen resistance." (PMID 36808875, 2023). "On the other hand, LATS1 expression was significantly elevated in breast cancers harboring an inactivating mutation in the NCOR1 gene, relative to those harboring wild-type NCOR1." (PMID 36443319, 2022). "Here the authors report that LATS1 limits the progression of luminal breast cancer by associating with NCOR1 nuclear corepressor to repress ERα-downregulated genes in luminal cells." (PMID 36443319, 2022). "NCOR1 is mutated in bladder cancer, breast cancer, and metastatic castration-resistant prostate cancer." (PMID 34503224, 2021). "We put our attention on NCOR1, as it was the only one associated with detrimental outcome in a significant manner in all breast cancer subtypes." (PMID 30485330, 2018). "In our article, we found that NCOR1 mutations in breast cancer are mainly missense and truncating, and produce a deleterious or damaging effect, leading to a nonfunctional protein." (PMID 30485330, 2018). "Notably, in TCGA ERα+ breast cancer, deleterious mutations and deep deletion of NCOR1, the gene coding NCoR, were observed." (PMID 27375289, 2016). "NCOR1 Nuclear Receptor Corepressor 1 mediates transcriptional repression by certain nuclear receptors, and has a known role in cancer, being associated with breast cancer, esophageal cancer and prostate cancer." (PMID 25148247, 2014). "Altogether, retention of proper LATS1 and NCOR1 activity appears to be beneficial for the survival of luminal breast cancer patients." (PMID 36443319, 2022). "Together, these results strongly suggest that LATS1 augments NCOR1-driven gene repression to promote luminal fate in human and mouse breast cancer cells." (PMID 36443319, 2022). "In the present study, we demonstrated that TNFα specifically enhances tamoxifen efficacy via NCOR1 to suppress the growth of ERα-positive breast cancer." (PMID 34073371, 2021). "Several studies revealed that NCOR1 has the characteristics of tumor suppressor including glioblastoma, malignant melanoma and breast cancer." (PMID 31661545, 2019). "To explore this idea, we evaluated NCOR1 at a transcriptomic level in relation with outcome in the different breast cancer subtypes." (PMID 30485330, 2018). "Examples include mutations in the ARID1A gene occurring in a subset of ovarian cancers and breast cancers along with mutations in the MLL2, MLL3, SMARCD1, NCOR1 and ARID1B genes found in a subset of breast cancers." (PMID 25468711, 2015). "Much of the antagonistic ER response to tamoxifen is mediated by NCoR1; and reduced NCoR1 expression in ER-positive primary breast cancers predicts for tamoxifen resistance and early metastatic relapse." (PMID 17407600, 2007). "This apparent mutual exclusivity between NCOR1 mutations and LATS1 downregulation suggests that NCOR1 inactivation and decreased LATS1 expression may have a redundant impact on breast cancer, in agreement with their proposed shared mechanism of action." (PMID 36443319, 2022).
breast carcinoma (continued). "Interestingly, previous studies demonstrated that the level of NCOR1 mRNA is correlated with a significantly shorter relapse-free survival and with the ERα status of breast cancer patients." (PMID 34073371, 2021). "To verify this hypothesis, in the present study we examined the specific effect of TNFα on the promotion of tamoxifen sensitivity in ERα-positive breast cancer and identified NCOR1 as a key regulator acting downstream of TNFα." (PMID 34073371, 2021). "Altogether, our results indicated that pharmacological or genetic disruption of NCOR1 could be an efficient targeted therapy for overcoming tamoxifen resistance in ERα-positive breast cancer." (PMID 34073371, 2021). "To verify this hypothesis, we investigated whether the dynamics of NCOR1 protein levels upon TNFα treatment differed between ER-positive MCF7 breast cancer cells and ER-negative MDA-MB-231 cells." (PMID 34073371, 2021). "Thus, we set out to identify novel single nucleotide polymorphisms (SNPs) within SRC-1 (NCoA1), SRC-3 (NCoA3, AIB1), NCoR (NCoR1), and SMRT (NCoR2), and test the most promising SNPs for associations with breast cancer risk." (PMID 20003447, 2009). "GGT1 has a suggested function in pancreatic carcinogenesis, whereas NCOR1 is part of a corepressor complex with histone deacetylase 3 (HDAC3) and may act as an oncogene in thyroid cancer, while ERCC5 polymorphisms were reported in breast cancer." (PMID 35205822, 2022). "To examine whether NCOR1 affects breast cancer development in vivo, we generated xenograft mouse models by injecting either parental or NCOR1-silenced MCF7 or MDA-MB-231 cells to the subcutaneous space of immunocompromised mice, and measured tumor weight 3 weeks after inoculation." (PMID 34073371, 2021). "Thus, we initially examined that whether NCOR1 expression is specifically regulated by TNFα in MCF7 ERα-positive breast cancer cells." (PMID 34073371, 2021). "The staining patterns of LATS1 and NCOR1 proteins were remarkably similar in PyMT mouse and MCF7 human mammary carcinoma cells." (PMID 36443319, 2022). "Our novel mutations in NCOR1, MUC4, and MUC16 genes should be validated in further mechanistic studies and translational studies so that those mutations might serve as predictive biomarkers or therapeutic targets for patients with CDK4/6 inhibitor-resistant breast cancer." (PMID 33504001, 2021). "Similar roles for NCOR1 and NCOR2/SMRT appear in the development of breast cancer and Tamoxifen resistance." (PMID 23098689, 2013). "Therefore, in luminal breast cancer and basal-like breast cancer cells, FOXF2 differentially modulates the transcription of WNT2B and FZD1 by enlisting NCoA3 and NCoR1, respectively." (PMID 40003882, 2025). "Importantly, also in human luminal breast cancer MCF7 cells, depletion of either NCOR1 or LATS1 increased the levels of H3K27ac and upregulated NCOR1-repressed genes." (PMID 36443319, 2022). "Consistently with the specific pro-proliferative function of NCOR1, NCOR1 knockdown induced apoptosis selectively in ERα-positive but not in ERα-negative breast cancer cells." (PMID 34073371, 2021). "Next, to determine whether NCOR1 affects the proliferation of breast cancer cells, we transfected MCF7 and MDA-MB-231 cells with short-hairpin RNAs (shRNAs) targeting NCOR1 (sh-NCOR1)." (PMID 34073371, 2021).
breast carcinoma (continued). "Furthermore the ability of steroidal nuclear receptor such as the AR and ERα to bind NCOR1 and NCOR2/SMRT is important to therapeutic exploitation with receptor antagonists in prostate and breast cancer." (PMID 23098689, 2013). "Elevated levels of NCOR1 occur in ERα negative breast cancer cells and in turn attenuate anti-mitotic actions of VDR." (PMID 23098689, 2013).
prostate carcinoma (16 papers, 2012 to 2025). A carcinoma that arises from epithelial cells of the prostate gland. "Our data suggest that Nuclear receptor corepressor (NCOR1) is involved in the maintenance of mitochondrial membrane potential in prostate cancer cells, and loss of NCOR1 may contribute to prostate cancer progression." (PMID 33058520, 2020). "NCOR1 malfunctioning is involved in cell proliferation and carcinogenesis in breast, colorectal, bladder, cervical, and prostate cancers." (PMID 41009328, 2025). "The AR-SIAH2 interaction has been most extensively studied in prostate cancer where it regulates hormone sensitivity of tumor cells in conjuction with NCoR1, another SIAH2 substrate that also interacts with REVERBα." (PMID 35789210, 2022). "The phosphorylation of NCOR1 was shown to play a role in transcriptional regulation in prostate cancer and in the liver in mice." (PMID 28390392, 2017). "Our finding is consistent with a previous report that the NCoR1 protein is highly elevated in androgen-independent prostate cancer cell lines PC-3 and DU145 when compared with LNCaP and RWPE1 cells." (PMID 23669876, 2013). "VDR recruits NCOR1 to negatively regulate vitamin-D3-mediated transcription and physical recruitment of NCOR1 on VDR gene targets was associated with altered repression of chromatin marks in prostate cancer." (PMID 34503224, 2021). "Past work has established links with cancer for some of these genes; for example, NCOR1, a nuclear co-repressor with 14 isoforms detected, has been postulated to regulate retinoic acid and thyroid hormone receptor protein levels and to disrupt PPARα/γ signaling in prostate cancer." (PMID 26939613, 2016). "Previous studies have found that NCOR1 and KMT2C/D play oncogenic roles in bladder cancer, colorectal cancer, prostate cancer, and lymphomagenesis." (PMID 36072793, 2022).
atherosclerosis (10 papers, 2018 to 2024). A disease characterized by the build-up of fatty material and calcium deposition in the arterial wall resulting in partial or complete occlusion of the arterial lumen. "In this review we describe the function of NCOR1 as a central immunometabolic regulator and focus on its role in atherosclerosis and associated immunometabolic diseases." (PMID 33117357, 2020). "To test this hypothesis, we studied the effects of liver-deficient Ncor1 mice that were fed a high-cholesterol diet for 12 weeks on atherosclerosis." (PMID 37349757, 2023). "Here, NCOR1 deletion attenuating atherosclerosis was attributed to upregulation of Cyp27a1 and Cyp3a11, resulting in altered bile compositions and increased fecal excretion of cholesterol." (PMID 38180064, 2024). "Recently, we demonstrated that the deletion of macrophage NCOR1 aggravates atherosclerosis by promoting CD36-triggered foam cell formation via PPARG derepression." (PMID 37349757, 2023). "In a previous report, macrophage NCOR1 has been shown to prevent atherosclerosis via activation of PPARγ." (PMID 38030614, 2023). "Our data demonstrate that liver-specific Ncor1 knockout mice on an atherosclerosis-prone background develop less atherosclerotic lesions than controls." (PMID 37349757, 2023). "In our atherosclerosis mouse model, deletion of hepatic Ncor1 led to reduced plasma cholesterol concentrations and diminished development of atherosclerotic lesions in the thoraco-abdominal aortae." (PMID 37349757, 2023). "Our data demonstrated that hepatic deletion of Ncor1 decreases atherosclerosis development by improving cholesterol tolerance." (PMID 37349757, 2023). "Our data suggest that hepatic Ncor1 deletion in mice decreases atherosclerosis development by reprograming bile acid metabolism and enhancing fecal cholesterol excretion." (PMID 37349757, 2023). "Our findings highlight a clear-cut phenotype: hepatic deletion of Ncor1 reduces atherosclerosis progression." (PMID 37349757, 2023). "The role of NCOR1 in macrophages in atherosclerotic cardiovascular disease is complex and has been shown to have a protective function during atherosclerosis, but an increase in inflammatory cytokines is also observed in response to PPARγ agonist stimulation." (PMID 38030614, 2023). "Although NCOR1 exerts a clear and important function in the pathogenesis of atherosclerosis and myocardial infarction, it is unclear how macrophage NCOR1 affects asthma." (PMID 38030614, 2023). "Among the different processes in which miR-199a-5p participate, several targets are implicated in atherosclerosis including ABCA1, ABCG1, Cav-1, HIF1A, CD38, NCOR1, and SIRT1 in human and mouse." (PMID 36407436, 2022). "Targeting immunometabolic pathways, e.g., those regulated by NCOR1, might become an attractive approach to prevent the development of atherosclerosis since they regulate various processes that promote the development of the disease." (PMID 33117357, 2020).